ENSG00000276140
Gene: Miscellaneous RNA gene on chromosome 8 (134,598,071 to 134,598,149, forward strand). Ensembl gene ENSG00000276140.
Gene Ontology:
Biological process: negative regulation of gene expression